MIR562 (microRNA 562)
Synonyms: hsa-mir-562; MIRN562
Gene: MicroRNA gene on chromosome 2 (232,172,653 to 232,172,747, forward strand). Ensembl gene ENSG00000207626.
Gene Ontology:
Biological process: miRNA-mediated post-transcriptional gene silencing
Homologues: Orthologues: chimpanzee ptr-mir-562 (100% identical), macaque mml-mir-562 (95% identical).
Diseases named in the same sentence as MIR562 in open-access papers:
MIR562 is named in the same sentence as 2 diseases in open-access papers, as found by Europe PMC text mining. Sharing a sentence is not in itself a finding about the gene and the disease. The quoted sentences say what the papers report.
glioblastoma (1 paper, 2021). The most malignant astrocytic tumor (WHO grade IV). "MIR562 has been shown to reduce the expression of c-MET in glioblastoma cells by directly binding to its 3’-UTR20." (PMID 34620846, 2021).
MIR562 also shares sentences with these, for which no sentence is quoted: cervical cancer (1 paper).